TRAF7 (TNF receptor associated factor 7)
Diseases named in the same sentence as TRAF7 in open-access papers (continued):
Sharing a sentence is not in itself a finding about the gene and the disease.
breast carcinoma (7 papers, 2016 to 2025). "Additionally, TRAF7 altered expression is associated with poorer prognoses in hepatocellular carcinoma, breast cancer, and prostate cancer." (PMID 41372821, 2025). "Interestingly several X10/IGF1-enriched mutations were observed, including Ezh2, Hras, and Traf7, of which Ezh2 and Hras are prominent modulators of human breast cancer." (PMID 28173837, 2017). "The impact of the hypermethylated TRAF7 gene has been reported in breast cancer and it is consistent with our results that this gene plays an important role in colorectal carcinogenesis." (PMID 27688749, 2016). "A study showed that downregulation of TRAF7 is correlated with poor prognosis in breast cancer development." (PMID 27688749, 2016).
mesothelioma (6 papers, 2018 to 2025). A usually malignant and aggressive neoplasm of the mesothelium which is often associated with exposure to asbestos. "Recurrent mutations in the TRAF7 gene are observed in mesothelioma cells." (PMID 29587439, 2018). "TRAF7 belongs to tumor necrosis factor (TNF) receptor-associated factors (TRAFs) possessing E3 ubiquitin ligase activity, and it was shown to promote ubiquitination of an apoptosis inhibitor, FLIP, which is increased in mesothelioma cells." (PMID 29587439, 2018). "Finally, TRAF7 is also an important biomarker of indolent disease in mesothelioma." (PMID 41372821, 2025). "There are six different fusions of TRAF7 and other genes detected in human cancers, including TRAF7-LRRC1 in lung cancer, GFER-TRAF7 in mesothelioma, CORO7-TRAF7 in glioma, TRAF7-MAPK8IP3 in bladder cancer, and TRAF7-RAB26 and E4F1-TRAF7 in ovarian cancer (TCGA)." (PMID 30294322, 2018). "TRAF7 was enriched in WDPMT, while common mesothelioma alterations (BAP1, NF2, CDKN2, and SETD2) were absent." (PMID 39167353, 2024).
hepatocellular carcinoma (5 papers, 2021 to 2025). A malignant tumor that arises from hepatocytes. "In other cases, TRAF7 acts as an oncogene and over expression is associated with cancer (hepatocellular carcinoma)." (PMID 41372821, 2025). "In hepatocellular carcinoma (HCC), TRAF7 overexpression is associated with an increased tumor size, higher-grade tumors, and poorer prognosis." (PMID 41372821, 2025). "Dr. Zhang found that hepatocellular carcinoma (HCC) with TRAF7 high expression was closely related with poor prognosis though repressing cell apoptosis." (PMID 40181456, 2025). "In this study, we systematically investigated the molecular mechanisms of TRAF7 in facilitating hepatocellular carcinoma (HCC)." (PMID 34775479, 2021). "For example, it was shown that TRAF7 associated with KLF4 through its ZF-CC region and was responsible for ubiquitination and proteasome-dependent degradation of KLF4 through its RING-dependent E3 ubiquitin ligase activity to promote hepatocellular carcinoma progression." (PMID 37583551, 2023). "Additionally, other research has shown that TRAF7 influences KLF4 by interacting with its N-terminus and promoting its degradation through ubiquitination in hepatocellular carcinoma (HCC)." (PMID 40181456, 2025).
developmental delay (4 papers, 2021 to 2025). "Germline mutations in TRAF7 are associated with a syndrome characterized by developmental delay, congenital heart disease, limb anomalies, and dysmorphic features." (PMID 41372821, 2025). "Germline mutations in TRAF7 lead to developmental delays and the dysmorphic features associated with TRAF7 syndrome." (PMID 41372821, 2025). "Multiple germline mutations in TRAF7 have been reported in >50 individuals with developmental disorders mainly featuring cardiac, facial, and digital anomalies with developmental delay, suggesting a critical role for TRAF7 in early development." (PMID 38178633, 2024). "It has been shown recently that heterozygous missense variants in TRAF7 lead to combined developmental delays and congenital malformation called TRAF7 syndrome,19,20) indicating that TRAF7 is crucial for development." (PMID 33840674, 2021). "Germline variants in tumor necrosis factor receptor-associated factor 7 (TRAF7) gene have recently been described in about 50 patients with developmental delay and cardiac, facial, and digital anomalies (CAFDADD)." (PMID 34513876, 2021). "This syndrome in humans was recently termed TRAF7-related cardiac, facial, and digital anomalies with developmental delay (CAFDADD) or TRAF7 syndrome." (PMID 41372821, 2025).
malignant mesothelioma (4 papers, 2020 to 2025). A malignant neoplasm of the pleura or peritoneum, arising from mesothelial cells. "The deletion of TRAF7 was found in 67% of malignant mesothelioma patients’ malignant cells in pleural fluids." (PMID 34775479, 2021). "TRAF7 also serves as a biomarker for adenomatoid tumors of the genital tract, which are benign serosal mesothelial tumors with a favorable prognosis, distinguishing them from malignant mesothelial tumors that have a much poorer prognosis." (PMID 41372821, 2025). "Alterations in TRAF7 have also been reported in malignant mesotheliomas." (PMID 32545767, 2020). "Well-differentiated papillary mesothelioma is genetically defined by TRAF7 or CDC42 alterations, which are mutually exclusive, and differentiate them from malignant mesothelioma." (PMID 41372821, 2025).
perineurioma (4 papers, 2018 to 2025). A usually benign perineurioma not associated with a nerve, arising from the soft tissues. "In particular, loss-of-function genetic alterations of TRAF2 and TRAF3 are frequently detected in B cell malignancies, and the rates of missense mutations of TRAF7 are overwhelmingly high in adenomatoid tumors, secretory meningiomas and perineuriomas." (PMID 30294322, 2018). "Intraneural perineuriomas harbor missense mutations in TRAF7, whereas soft tissue perineuriomas commonly show deletions of chromosome 22q (NF2) and deletions of chromosome 17q11 (NF1), as well as chromosome 2p deletions or rearrangements or deletions of chromosome 10q (sclerosing variant)." (PMID 37046591, 2023). "Although intraneural perineurioma had been considered as a reactive process (localized hypertrophic neuropathy), the identification of clonal cytogenetic abnormalities involving chromosome 22 as well as the recent discovery of TRAF7 mutations in 60% of cases seems to confirm its neoplastic nature." (PMID 35741273, 2022). "TRAF7 mutations have also been identified in 60% of intraneural perineuriomas but not in extraneural perineuriomas." (PMID 41372821, 2025). "Interestingly, TRAF7 mutations, seen in intraneural perineuriomas, are not observed in the soft tissue counterpart." (PMID 35741273, 2022).
prostate carcinoma (4 papers, 2023 to 2025). A carcinoma that arises from epithelial cells of the prostate gland. "Additionally, TRAF7 overexpression has also been implicated in the pathophysiology of prostate cancer through its effect on Homeobox A5 (HOXA5)." (PMID 41372821, 2025).
brain tumors (3 papers, 2022 to 2025). "The function of TRAF7 mutation has been limited reported in brain tumors, and few studies pay attention to selecting therapeutic medicine depending on the TRAF7 expression in the management of glioma." (PMID 40181456, 2025). "Somatic mutations within the coiled-coil (CC) domain and WD40 repeat domain of TRAF7 could cause brain tumors, while germline pathogenic mutations contribute to severe developmental abnormalities." (PMID 38178633, 2024).
glioblastoma (3 papers, 2023 to 2025). The most malignant astrocytic tumor (WHO grade IV). "Detailed examination indicated that the highest expressions of TRAF1, TRAF2, TRAF3, TRAF5, and TRAF7 were in Cholangiocarcinoma (CHOL), while TRAF4 was most expressed in Uterine Corpus Endometrial Carcinoma (UCEC) and TRAF6 in Glioblastoma multiforme (GBM)." (PMID 38825674, 2024).
pancreatic cancer (3 papers, 2021 to 2025). "Our data demonstrate that MT1G promotes the degradation of NF-κB p65 subunit via tumor necrosis factor receptor-associated factor 7 (TRAF7), thus limiting activin A secretion and suppressing pancreatic cancer cell stemness." (PMID 33537082, 2021). "The findings from this assessment indicated that TRAF2, TRAF3, TRAF5, and TRAF7 are effective in predicting the outcomes of pancreatic cancer." (PMID 38825674, 2024). "In addition, TRAF4, TRAF5, TRAF6, and TRAF7 demonstrate correlations with the degree of pancreatic cancer differentiation." (PMID 38825674, 2024). "Notably, TRAF2 and TRAF7 demonstrate a significant positive correlation with the chemotherapeutic agents fluorouracil and gemcitabine, which are commonly used in the treatment of pancreatic cancer." (PMID 38825674, 2024).
Chordoid Meningioma (2 papers, 2020 to 2022). A WHO grade II, usually recurring meningioma characterized by the predominance of tissues that are histologically similar to chordoma. "Together, the mutations in TRAF7, KLF4, AKT1, and VHL genes were mutually exclusive and occurred in 64.7% of the well-differentiated chordoid meningiomas from ED group #3." (PMID 31963394, 2020). "Genetically, previous studies found that chordoid meningiomas had sparce NF2, TRAF7, KLF4, SMO, AKT1 and SMARCB1 mutations common to non-chordoid meningioma." (PMID 35440040, 2022).
glioma (2 papers, 2018 to 2025). A benign or malignant brain and spinal cord tumor that arises from glial cells (astrocytes, oligodendrocytes, ependymal cells). "Our results demonstrated that TRAF7-deficient glioma cells exhibited increased sensitivity to lomustine in a dose-dependent manner." (PMID 40181456, 2025). "• High TRAF7 expression is linked to glioma progression and recurrence." (PMID 40181456, 2025). "Therefore, AUC results suggested that higher TRAF7 expression may act as a potential diagnostic marker in glioma." (PMID 40181456, 2025). "TRAF7 has the potential to be a prognostic indicator and a prospective therapeutic target in glioma patients." (PMID 40181456, 2025). "Our rescue assays further confirmed that TRAF7 promotes glioma progression in a KLF4-dependent manner." (PMID 40181456, 2025). "We found that downregulation of TRAF7 expression inhibited glioma progression and recurrence, as validated by the TCGA, CGGA datasets, and the tumor tissue of glioma patients." (PMID 40181456, 2025). "High-level expressions of TRAF7 mRNA were shown in human glioma samples in TCGA database, including high-grade gliomas (HGGs, III-IV grade) and low-grade gliomas (LGGs, I-II grade)." (PMID 40181456, 2025). "Compared with CCNU or TRAF7 inhibition alone, our results found that the count of senescent cells (measured via ß-galactosidase-senescence assay) was markedly increased to glioma sh-TRAF7 cells treated with CCNU." (PMID 40181456, 2025). "To explore the expression of TRAF7 in glioma in vitro, we determined the TRAF7 protein and mRNA levels in six human glioma cell lines, including A172, T98G, U87, LN229, U251, and Hs683." (PMID 40181456, 2025). "Overall, the TRAF7 repression group and lomustine-treated group induced a senescence state, especially in the combination treatment group in two glioma cells." (PMID 40181456, 2025). "• TRAF7 knockdown inhibits glioma cell proliferation, invasion, and migration via cellular senescence and cell cycle arrest." (PMID 40181456, 2025). "The functions of TRAF7 combined with lomustine in glioma were assessed by both in vitro, in vivo and patient-derived primary and recurrent glioma stem cell (GSC) assays." (PMID 40181456, 2025). "In vitro, TRAF7 knockdown significantly inhibits glioma cell proliferation, invasion, and migration." (PMID 40181456, 2025). "The expression of TRAF7, cellular senescence and cell cycle arrest pathways in glioma tissues and cell lines was detected by real-time quantitative PCR (RT-qPCR), western blotting and immunohistochemistry." (PMID 40181456, 2025). "In the present study, we identified CCNU as a clinically applicable drug that synergizes with TRAF7 inhibitors in glioma through promoting a senescence-state." (PMID 40181456, 2025). "Our findings could represent a significant step toward enhancing the understanding of TRAF7 signaling, which may be crucial for developing more precise therapeutic strategies in the progression and recurrence of glioma." (PMID 40181456, 2025). "Our study suggested that the second-line lomustine regulating cellular senescence could be recommended as the optimal choice in the progression and recurrence glioma patients with high-level TRAF7 expression." (PMID 40181456, 2025). "Here, we generated a comprehensive analysis of TRAF7 in glioma." (PMID 40181456, 2025). "In vivo, TRAF7 knockdown combined with lomustine treatment effectively suppressed glioma growth." (PMID 40181456, 2025). "We also explored the protein expression of TRAF7 at different glioma cell lines." (PMID 40181456, 2025). "Lomustine, regulating cellular senescence and cell cycle could be the priority choice in glioma patients with high-level TRAF7 expression." (PMID 40181456, 2025). "The TRAF7 expression of glioma whole-brain sections was consistent with the in vitro results." (PMID 40181456, 2025). "• Lomustine may be prioritized for glioma patients with high-level TRAF7 expression." (PMID 40181456, 2025).
glioma (continued). "However, the therapeutic role and potential mechanism of TRAF7 in glioma patients remain largely unknown." (PMID 40181456, 2025). "Our results showed that TRAF7 restraint and lomustine (CCNU) induced a senescence-state to inhibit the progression and recurrence in glioma." (PMID 40181456, 2025). "TRAF7 RNA-seq was analysed with the TCGA and CGGA databases between glioma tissues and normal brain tissues." (PMID 40181456, 2025). "However, the molecular mechanisms of TRAF7 through senescence in glioma remain largely unknown." (PMID 40181456, 2025). "Our research also found that the absence of TRAF7 expression inhibited glioma growth while promoting SASP expression, confirmed by the in vitro experiments." (PMID 40181456, 2025). "Thus, inhibition of TRAF7 checkpoint may performed a promising therapeutic strategy and CCNU markedly enhances treatment response in high-expression TRAF7 subtype of glioma." (PMID 40181456, 2025). "TRAF7 could be used as a predictive biomarker and the potential therapeutic target among National Comprehensive Cancer Network (NCCN) treatment guidelines in the progression and recurrence of glioma." (PMID 40181456, 2025).
lung carcinoma (2 papers, 2018 to 2025). "For example, TRAF7 mutation was found in both univariate analysis and in the OncoCast model to be prognostically significant in lung cancer metastatic to the spine." (PMID 40647516, 2025).
adenoma (1 paper, 2016). A neoplasm arising from the epithelium. "We identified hypermethylated CpG sites in the following genes: L3MBTL1, NKX6-2, PREX1, TRAF7, PRDM14, and NEFM with the number of CpG sites being 14, 17, 10, 16, 6, and 6, respectively, after pairwise analysis of normal versus adenoma, adenoma versus cancer, and normal versus cancer." (PMID 27688749, 2016).
Angiomatous Meningioma (1 paper, 2014). A WHO grade I meningioma characterized by the presence of small and medium sized vessels that predominate over the meningioma cells. "To determine if established cancer genes are mutated in angiomatous meningioma, we sequenced all exons from 560 cancer associated genes and performed amplicon sequencing of all exons from TRAF7 and the exon encoding the KLF4 K409 amino acid residue that were not present in the OPv2 gene set." (PMID 25347344, 2014).
atherosclerosis (1 paper, 2018). A disease characterized by the build-up of fatty material and calcium deposition in the arterial wall resulting in partial or complete occlusion of the arterial lumen. "Under the 32 identified miR-99a target genes two are related to atherosclerosis: TRAF7 modulates activity of NF-κB transcription factor, and may thus contribute to pro-atherogenic inflammatory stimulation." (PMID 29777114, 2018).
brain hemorrhage (1 paper, 2023). "Our finding that postnatal endothelial-specific deletion of Traf7 resulted in brain hemorrhage is in agreement with previously published results demonstrating that Mekk3 is required for the integrity of postnatal vasculature." (PMID 37583551, 2023).
cardiac hypertrophy (1 paper, 2025). "Genes implicated in pathways associated with axonal guidance, Wnt/Ca2+ signaling, and cardiac hypertrophy, among others, were enriched in TRAF7 mutant patients with TRAF7 syndrome." (PMID 41372821, 2025). "Increased TRAF7 activity regulates the degradation of apoptosis signal-regulating kinase-1 phosphorylation and induces cardiac hypertrophy in a mouse model." (PMID 41372821, 2025).
cerebrovascular diseases (1 paper, 2025). "Recent studies have provided new insights into the role of TRAF7 in endothelial dysfunction and the contributions to cerebrovascular diseases." (PMID 40868928, 2025). "Potential interventions, including pharmacological modulation and gene therapy approaches targeting TRAF7, could restore endothelial homeostasis and protect against the progression of cerebrovascular diseases." (PMID 40868928, 2025).
Chlamydia infection (1 paper, 2024). "Here, we investigated the Tri1:TRAF7 interaction because Tri1 is not a well-characterized Inc, and because TRAF7 is involved in signaling pathways that are relevant for Chlamydia infection (14, –, 19)." (PMID 38814079, 2024).
cognitive decline (1 paper, 2025). "Gene therapy approaches are also being explored as a means to titrate TRAF7 expression, potentially preventing the cascade of events that lead to endothelial senescence, BBB breakdown, and subsequent cognitive decline." (PMID 40868928, 2025).
Cognitive impairment (1 paper, 2025). Abnormal cognition is characterized by deficits in thinking, reasoning, or remembering. "Understanding TRAF7’s function opens avenues for novel therapeutic strategies aimed at mitigating age-related vascular decline and cognitive impairment." (PMID 40868928, 2025).
colitis (1 paper, 2023). Inflammation of the colon. "The AS events of Bnip2, Traf1, and Traf7 that enriched in apoptotic process in acute colitis models have been verified by PCR." (PMID 37158534, 2023).
colorectal cancer (1 paper, 2019). A primary or metastatic malignant neoplasm that affects the colon or rectum. "Thus, strategies to deactivate the NF-kB pathway, such as blocking TRAF7, might be useful to enforce the infiltration of cytotoxic T cells and to kill colorectal cancer cells." (PMID 31998649, 2019).